RNU6-994P (RNA, U6 small nuclear 994, pseudogene)
Gene: Small nuclear RNA gene on chromosome 20 (63,337,339 to 63,337,449, forward strand). Ensembl gene ENSG00000222439.
Homologues: Orthologues: chimpanzee U6 (97% identical), macaque U6 (87% identical), macaque U6 (71% identical), dog U6 (67% identical), dog U6 (66% identical), dog U6 (65% identical), dog U6 (62% identical), guinea pig U6 (59% identical), dog U6 (59% identical), rabbit U6 (59% identical), dog U6 (58% identical), rabbit U6 (57% identical), and 3 more. Paralogues in human: RNU6-1024P (69% identical), RNU6-71P (69% identical), RNU6-1011P (68% identical), RNU6-205P (68% identical), RNU6-703P (68% identical), RNU6-838P (68% identical), RNU6-106P (68% identical), RNU6-1201P (68% identical), RNU6-1290P (68% identical), RNU6-12P (68% identical), RNU6-1322P (68% identical), RNU6-13P (68% identical), and 1280 more.